EGF (epidermal growth factor)
Diseases named in the same sentence as EGF in open-access papers (continued):
Sharing a sentence is not in itself a finding about the gene and the disease.
infection (continued). "In this work, we described the dynamics of the production of EGF, FGF, PDGF, and TGFβ from initial infection and manifestation of skin lesions to the early stages of response to different treatment compounds." (PMID 30333964, 2018). "We demonstrated that the expression of PDGF, EGF, FGF, and TGFβ1 was induced at ID15 during the establishment of the experimental infection by L. (V) braziliensis." (PMID 30333964, 2018). "In this work, we analyzed the production of the growth factors EGF, TGFβ1, PDGF, and FGF during the infection by Leishmania parasites, the development of the injuries and the early response to treatment." (PMID 30333964, 2018). "The healing outcome of EGF, FGF-2, ofloxacin drops, and observation groups after eliminating infection ear." (PMID 28746231, 2017). "The infection rates differed significantly among the 4 groups; the EGF and FGF-2 groups had higher rates of otorrhoea, and the infection rate in the ofloxacin drops group was lower." (PMID 28746231, 2017). "This study suggests that the C-terminal region contains two immunogenic epidermal growth factor (EGF)-like domains which induce T-cell and antibody responses against P. vivax during natural infection in humans." (PMID 28243235, 2017). "In short, ALP as a S. eriocheiris surface protein, is critical for infection and further supports the role of ALP in S. eriocheiris infection by competitive effection of the EGF/EGFR axis of the target cells." (PMID 28184355, 2017). "Prior to the EGF pulse, EGFR surface levels were increased or decreased in UL135STOP or UL138STOP infection relative to that of WT-infected cells, as anticipated from our analysis of surface levels." (PMID 27218650, 2016). "At 4 h of infection, EHEC partially inhibited TNF-α-induced p65 phosphorylation and EGF-induced ERK1/2 phosphorylation, while a complete inhibition of both pathways was observed by EPEC infection." (PMID 27774437, 2016). "Our quantitative PCR data showed that three ligands, HB-EGF, AREG and EREG, displayed significant up-regulation at 60 min after infection with strain RS218, while the transcriptional levels of EGF, BTC and TGFα remained unchanged during the infection." (PMID 27711202, 2016). "EHEC infection also caused an increase of ERK1/2 phosphorylation in only 20% at 0.5 h of infection and co-stimulation with EGF after EHEC infection only increased 50–55% at 0.5, 1, and 2 h of infection and 30% at 4 h in comparison with EGF alone (100%)." (PMID 27774437, 2016). "The epidermal growth factor inhibitor Iressa, previously shown to inhibit VACV infection at the level of entry 33, was used as a positive control for bypass." (PMID 25869659, 2015). "For example STAT1 can be activated by type I interferon, STAT3 can be activated by growth factors (e.g. EGF, LIF) and NFκB can be activated by reactive oxygen species, infection and other inflammatory cytokines, including IL-1β." (PMID 26678048, 2015). "The results showed that in EGF stimulated AGS cells, the level of DAG increased obviously and pre-infection with Ad-PKG II and treatment with 8p-CPT-cGMP inhibited the formation of DAG caused by stimulation with EGF." (PMID 23613900, 2013). "Depletion of the receptor in HEp-2 cells by specific siRNA, addition of EGF or blocking of the ligand-binding pocket with an anti-EGFR antibody significantly reduced both EB attachment and infection." (PMID 23633955, 2013). "Like hPIV3-C expression alone, hPIV3 infection enhanced ERK1/2 phosphorylation at the peak of induction, i.e. 10 min after adding EGF to the cells." (PMID 19806178, 2009). "Unstimulated (Nil), TB antigen stimulated (Ag) and antigen stimulated minus unstimulated (Ag-Nil) levels of EGF, sCD40L, and TGF-αAg, MIP-1βAg-Nil and VEGFNil were the most accurate single markers that differentiated between the two infection states." (PMID 19445695, 2009).
infection (continued). "One possible candidate expressed early during infection is the highly conserved vaccinia growth factor (VGF), an epidermal growth factor (EGF)-like growth factor." (PMID 19388902, 2009). "Infection of hCMEC/D3 with N. meningitidis for 4h did not further increase S1P or EGF mediated phosphorylation of EGFR." (PMID 38033162, 2023). "EGF is a protein important for the maintenance of epithelial cell integrity, and HRV-infected children have increased levels of it in their saliva at an acute stage of infection." (PMID 37766270, 2023). "Our data clearly showed a higher level of infection in the presence of filopodia vs. in the absence of filopodia (compare bradykinin/EGF experiments with ML-141)." (PMID 35746622, 2022). "With the systematic review and evaluation of the currently available evidence, we conclude that the therapeutic use of growth factors including EGF, FGF and GM-CSF is effective and safe in the treatment of acute skin wounds, especially in the case of wounds entailing higher risks of infection." (PMID 35265723, 2022). "HRV16 infection also led to a significant increase in expression of genes involved in EMT (e.g., COL1A1, MMP9, SNAI1, and ZEB2) and growth factors (e.g., ~ fourfold for EGF and FGF2, and to a lesser extent TGFB1)." (PMID 34140575, 2021). "To corroborate the ELISA results identifying human EGF in growth media, we determined that HUVEC proliferation in response to Bb infection or VEGF treatment could be blocked by tyrphostin AG1478; a potent and selective EGFR inhibitor." (PMID 32302357, 2020). "In contrast, infection did not significantly impact cellular expression of EGF, FGF2, and VEGFB, and FGF1 expression was not reliably detected." (PMID 31569536, 2019). "Aliquots from the infected hNSCs were then differentiated by culturing them in DMEM/F12 with N2 and B27 supplements (without bFGF or EGF) to assess the efficiency of infection by counting the number of ZsGreen1 positive cells." (PMID 31227736, 2019). "Infection by L. (V) braziliensis induced the expression of all the growth factors in ID15, with levels of induction with respect to healthy hamsters of: PDGF 0.4 ± 0.1, EGF 3.9 ± 0.2, FGF 1.1 ± 0.5, and TGFβ1 0.4 ± 0.2." (PMID 30333964, 2018). "Since activation of the EGF receptor is important for H. pylori-induced gastrin promoter activation, the absolute levels of mRNA expression were next determined for the EGF family members (HB-EGF, AR, EGF, TGF-α, BTC, epigen, and epiregulin) using qRT-PCR at 1, 2.5, and 5 h post-infection." (PMID 29379775, 2017). "The healing outcome of EGF, FGF-2, ofloxacin ear drop, and observation group of infection ear." (PMID 28746231, 2017). "Interestingly, co-stimulation with EGF following ETEC infection blocked ERK1/2 phosphorylation at 0.5 and 1 h of infection, while at 2 and 4 h only reached 55% of the positive control." (PMID 27774437, 2016). "Interestingly, co-stimulation with EGF after EPEC infection decreased ERK1/2 phosphorylation (75, 45, 30, and 0% at 0.5, 1, 2, and 4 h) in comparison to the co-stimulation after HB101 infection (100% at all tested times)." (PMID 27774437, 2016). "In studies exploring the ERC in infection, Britt and colleagues reported that EGF did not localize to the VAC." (PMID 27218650, 2016). "We analyzed phosphorylation of Y1068 following an EGF pulse in the context of infection with or without pUL135 and pUL138." (PMID 27218650, 2016). "EPEC only caused a modest increment of ERK1/2 phosphorylation at 0.5 h of infection, but no other infection time points, representing about 25% of levels induced by the positive EGF control." (PMID 27774437, 2016). "The formulation of CDP gels with and without EGF induced no infection of the wounds, whereas the control group showed wound infection at 4 and 8 days after operation." (PMID 25110681, 2014).
infection (continued). "Perhaps, then, the primary function of EGF in keratinocyte activation is in wound healing and re-epithelialization, rather than in immune responses and in fighting infection." (PMID 23391100, 2013). "HCMV has been demonstrated to interact with integrin, EGF and PDGF receptors during infection." (PMID 22870300, 2012). "Dex/EGF treated cells (which do not normally express TFN in many cells) were induced to do so following infection with Ad-CMV-LAP." (PMID 21048969, 2010). "Because the total protein level of EGFR prior to EGF stimulation was low in cells infected through PilC1 (left panel-), the strong reduction in EGFR phosphorylation was probably due to the depletion of the total EGFR pool upon PilC1-mediated infection." (PMID 19718432, 2009). "At 24 hours post infection the cells were induced to differentiate in the presence or absence of EGF and then harvested 48 hours later." (PMID 16984645, 2006). "In the absence of EGF, infection with the DN-Akt adenovirus did not affect the DIP-induced promotor activity, but DN-Akt partially rescued the EGF-induced inhibition of β-casein promotor luciferase activity compared to LacZ vector control." (PMID 16984645, 2006). "Transcriptome analysis of the red alga P. yezoensis during oomycete infection revealed that three lectin genes (PRRs) were upregulated after infection, whereas EGF- and LysM-containing genes could not be found." (PMID 34884652, 2021). "The expression levels of PDGF, EGF, FGF, and TGFβ1 were calculated by the ΔΔCT method and expressed as the mean ± SD of the number of times that each factor was induced with respect to healthy skin before infection (ID0), during the development of the lesion (ID15 and ID30)." (PMID 30333964, 2018). "Co-stimulation experiments showed partial inhibitory effects in which, EGF-induced ERK1/2 phosphorylation does not reach 100% but at intermediate times ERK1/2 phosphorylation was not significantly different of those of late times of infection." (PMID 27774437, 2016). "Thus, lowest responses at 1 and 2 h of infection with the intracellular bacteria were recovered to 50% by co-stimulating with EGF but at no time tested the EGF co-stimulation after infection reached a 100%." (PMID 27774437, 2016). "However, some ion channel genes (calcium channel or potassium channel) appeared to be down-regulated; and growth factors (EGF, EGR, VGF etc.)were also down; and eventually the transcription factors such as the elongation factors were also reduced during the OPPV infection." (PMID 26950733, 2016). "Interestingly, hPIV3 infection induced a significant level of Elk1 activity in the absence of EGF stimulation." (PMID 19806178, 2009). "Similarly to non-infected cells, PilC2-mediated infection left ME180 cells permissive for EGFR phosphorylation upon EGF stimulation." (PMID 19718432, 2009). "This could relate to the fact that hPIV3 infection also induces low levels of eIF4E and S6 phosphorylation in the absence of EGF stimulation." (PMID 19806178, 2009). "However, when the immune response is regulated by TGFβ1 and the infection is effectively established at ID30, its expression is negatively regulated, due to the fact that the macrophages and fibroblasts, as its main sources, are in a context in which the production of EGF is diminished." (PMID 30333964, 2018). "Other studies have indicated that epidermal growth factor (EGF), macrophage inflammatory protein (MIP)-1β, IL-1α, transforming growth factor (TGF)-α, soluble CD40 ligand (sCD40L), vascular endothelial growth factor (VEGF), IP-10, TNF-α, IL-12(p40), might discriminate between active TB and infection." (PMID 23691173, 2013). "Although infection in SFM increased the number of cells in G1 phase, the depletion conditions did not alter the cell cycle profiles significantly from that in CM or in SFM plus EGF, suggesting cell cycle changes alone could not account for infection inhibition." (PMID 22346752, 2012).
infection (continued). "Conversely, although the EGF peptide independently activated EGFR, its treatment upon vΔVGF infection did not achieve full EGFR activation, reducing phosphorylation levels to those similar to the uninfected cells." (PMID 39817770, 2025). "Two chemokines in analyte cluster 2, EGF and CCL11, were also uniformly expressed by all patient clusters independent of infection outcome and are also involved in cell recruitment." (PMID 39966757, 2025). "EGFR protein levels however did not change in response to infection and even declined at 8h p.i., suggesting a partial turnover of EGFR at later time points of infection following EGF-mediated EGFR activation." (PMID 38033162, 2023). "Infection rate (in %) is given as mean ± SEM and the mean of EGF-non-treated control siRNA-treated cells was normalized to 100%." (PMID 31107240, 2019). "While the EGF and FGF levels decreased between day 15 and 30 of infection, the TGFβ1 increased and the PGDF levels did not change." (PMID 30333964, 2018). "Insect cells were infected with a multiplicity of infection (MOI) of 10 of control or EGFR baculovirus for 48 hours with and without additional EGF followed by detection of total and phosphorylated EGFR by Western Blot." (PMID 28586369, 2017). "The results showed that the triple deletion mutant was able to induce significant up-regulation of AREG and EREG after 60 min, while there was no up-regulation of HB-EGF, as well as EGF, BTC, and TGFα, after infection with the triple deletion mutant." (PMID 27711202, 2016). "Although the addition of albumin did not enhance infectivity in SFM (not shown), the addition of EGF and KGF in SFM dramatically restored infection in dose dependent manners." (PMID 22346752, 2012). "Recombinant human epidermal growth factor (EGF) (10 ng/ml) was used routinely as a positive control for each assay, as SGHPL-4 cells significantly migrate and invade in response to EGF, while infection with HCMV abrogates this response (data not shown)." (PMID 23116176, 2012). "In the case of PilC2-mediated infection, EGFR phosphorylation response to EGF stimulation was slightly lower in comparison to non-infected control cells." (PMID 19718432, 2009). "EGF stimulation induced the internalization of EGFR in both cell types, irrespective of infection." (PMID 38856640, 2024).
kidney disease (25 papers, 2013 to 2025). "Clusterin has been implicated in tubular protection and recovery in kidney injury models, while reduced urinary EGF is linked to impaired renal injury repair and worsened kidney disease outcomes." (PMID 40244015, 2025). "Among these, in the univariate analysis, only EGF/MCP-1 ratio was associated with kidney disease progression after adjusting for uACR." (PMID 39452561, 2024). "Notably, reduced urinary EGF levels have been associated with various kidney disorders." (PMID 40136513, 2025). "Deficiency in EGF and TGF-α signaling through EGFR has been shown to be an important modifier of kidney structure and function and a risk factor in renal diseases." (PMID 36752209, 2023). "Messenger RNA profile studies from kidney disease patients identified epidermal growth factor (EGF) as a peptide growth factor that correlated with the estimated glomerular filtration rate." (PMID 35271583, 2022). "EGF is expressed by cells within the ascending limb of the loop of Henle and the distal tubules and has been shown to have differing effects on renal disease pathology." (PMID 35355862, 2022). "Epidermal growth factor (EGF) has been found to be associated with the development and repair mechanisms of several renal diseases." (PMID 31906817, 2020). "Several signaling pathways, such as EGF, have been pinpointed to drive the progression of kidney disease in podocytes." (PMID 29549365, 2018). "Though CXCL10 and EGF have been reported altered in a variety of renal diseases, even in the kidney rejection, the network of CXCL10, EGF and STAT1 in BKVN has not been reported." (PMID 29567951, 2018). "It is known that urinary EGF levels decrease in more severe renal disease." (PMID 37020541, 2023). "Similarly, uPA, EGF, and Lipocalin-2 have demonstrated involvement in the pathology of renal disease." (PMID 35355862, 2022). "EGF could serve as a prognostic biomarker of kidney diseases because it is excreted partially in the urine." (PMID 35008447, 2021). "EGF expression within the kidney is decreased in several kidney diseases." (PMID 30241508, 2018). "Therefore, we hypothesize that stabilization of EGF and EGF receptor activation in a cell-selective context in the kidney tubules may ameliorate kidney disease progression." (PMID 32280839, 2020). "Urinary EGF levels have been shown to correlate with the severity of tubulointerstitial fibrosis in primary glomerulonephritis, and low urinary EGF has been shown to be a risk predictor of kidney progression in non-diabetic kidney diseases." (PMID 30241508, 2018). "Keeping this in mind, we focused on the potential role of urinary EGF as a biomarker in ADPKD, and left a comparison of the predictive value of urinary EGF in ADPKD versus in other kidney diseases beyond the scope of the present study." (PMID 36914219, 2023). "Taken together, these data suggest that the proteins ASC, IL-18, uPA, EGF, NGAL, and CRP contribute significantly to the inflammatory response in renal diseases." (PMID 35355862, 2022). "In animal models, it has been shown that capsaicin has beneficial effects on kidney function through acting as a diuretic in healthy and diabetic rats and reducing urinary epidermal growth factor (EGF) levels, a biomarker for kidney disease." (PMID 31817083, 2019). "Low urinary EGF levels have been found to be predictive of kidney function decline in non-diabetic renal diseases." (PMID 30241508, 2018). "The lack of protective effects of EGF and IFN-α seemed to be crucial for the progression of renal disease." (PMID 36499745, 2022). "The lack of EGF regenerative effects and IFN-α antiviral activity seemed crucial for renal disease progression." (PMID 36499745, 2022).